REN (renin)
Diseases named in the same sentence as REN in open-access papers (continued):
Sharing a sentence is not in itself a finding about the gene and the disease.
transient ischemic attack (4 papers, 2021 to 2024). A brief attack (from a few minutes to an hour) of cerebral dysfunction of vascular origin, with no persistent neurological deficit. "EQ5D-5L, EuroQol 5D questionnaire; IQR, interquartile range; NOAC, non-vitamin K antagonist oral anticoagulant; RAAS, renin–angiotensin–aldosterone system; TIA, transient ischaemic attack; VKA, vitamin K antagonist." (PMID 37151778, 2023).
urinary tract infection (4 papers, 2015 to 2025). "Diagnostic work up revealed a combination of a urinary tract infection, inadvertently low sodium provision with donor breast milk, and weak renin-angiotensin-aldosterone response." (PMID 26377549, 2015). "Investigations identified an Escherichia coli urinary tract infection (UTI), and further laboratory tests revealed markedly elevated serum renin and aldosterone levels, consistent with secondary PHA associated with UTI in infancy." (PMID 40904963, 2025).
abdominal aortic aneurysm (3 papers, 2012 to 2023). Enlargement and ballooning of the vessel that supplies arterial blood to the abdomen, pelvis and legs. "Multiple logistic regression analysis was conducted to identify whether the progression of abdominal aortic aneurysms could be attributed to increased plasma renin levels and activity." (PMID 37383707, 2023).
adrenal hypoplasia (3 papers, 2007 to 2023). "The elevated renin led to a diagnosis of adrenal hypoplasia, and it was considered necessary to add fludrocortisone treatment to the glucocorticoid replacement." (PMID 17223989, 2007). "The initial biochemical picture is similar to adrenal hypoplasia, CAH or secondary PHA and investigations should include plasma renin activity, aldosterone, 17-OHP, cortisol levels, renal ultrasound scan, urine cultures and a urine steroid profile." (PMID 24616761, 2013).
aortic valve disease (3 papers, 2014 to 2018). "This study revealed that several key element genes of the renin-angiotensin system were differentially expressed in the left atrium in MR patients in comparison with aortic valve disease patients and normal controls." (PMID 30581499, 2018). "Quantitative RT-PCR was used to compare gene expression in the renin-angiotensin system in the left atrium in MR patients, aortic valve disease patients, and normal subjects." (PMID 30581499, 2018). "This study showed that gene expression patterns of the renin-angiotensin system in the left atrium in MR patients with HF differed from those in aortic valve disease patients with HF and normal controls." (PMID 30581499, 2018). "Seventy-eight percent of MR patients and forty-two percent of patients with aortic valve disease received renin-angiotensin system blockers (P = 0.102)." (PMID 27907007, 2016). "Expressions of genes in the renin-angiotensin system, especially CTSA, LNPEP, and MAS1, in the left atrium in MR patients significantly differed from expressions of these genes in aortic valve disease patients and normal controls." (PMID 30581499, 2018). "Expressions of genes in the renin-angiotensin system, especially CTSA, LNPEP, and MAS1, in the left atrium in MR patients significantly differed from those in aortic valve disease patients and normal controls, and the differences were independent of circulating angiotensin II levels." (PMID 30581499, 2018).
arrhythmogenic right ventricular cardiomyopathy (3 papers, 2020 to 2023). "Among them, such as the PI3K-Akt signaling pathway, Rap1 signaling pathway, Arrhythmogenic right ventricular cardiomyopathy signaling pathway, Renin secretion signaling pathway." (PMID 32011476, 2020).
basal cell carcinoma (3 papers, 2017 to 2021). A carcinoma involving the basal cells. "KEGG enrichment analysis indicated upregulated DEGs were involved in Renin-angiotensin system (e.g., Agt, angiotensinogen) and Wnt signaling pathway (e.g., Dkk1), while downregulated DEGs participated in Basal cell carcinoma (e.g., Lef1)." (PMID 29121993, 2017). "As a result, 24 KEGG pathways were enriched for upregulated DEGs, including Renin-angiotensin system (e.g., Agt, angiotensinogen), Renin secretion (e.g., Agt), and Wnt signaling pathway (e.g., Dkk1), while 16 pathways were for downregulated DEGs, including basal cell carcinoma (e.g., Lef1)." (PMID 29121993, 2017).
Bradycardia (3 papers, 2022 to 2025). A slower than normal heart rate (in adults, slower than 60 beats per minute). "Studies of LEA in amenorrheic athletes have shown bradycardia and lower blood pressures due to alterations in the renin – angiotensin – aldosterone system." (PMID 40262556, 2025). "In myxedema, bradycardia, and decreased myocardial contractility, in combination with a reduced preload due to downregulation of T3-regulated liver-derived renin, leads to a significantly decreased cardiac output." (PMID 35530928, 2022).
brain injury (3 papers, 2020 to 2025). Acute and chronic (see also brain INJURIES, CHRONIC) injuries to the brain, including the cerebral hemispheres, CEREBELLUM, and brain STEM. "In models of traumatic brain injury, increased (pro)renin mRNA expression has been detected, and pharmacological inhibition of renin with aliskiren has been shown to reduce oxidative stress, glial activation, and spatial memory deficits." (PMID 40868980, 2025).
chronic lung disease (3 papers, 2019 to 2023). According to the definitions of the American and British Thoracic Societies, including pulmonary functional tests, X-rays, and CT scans for items such as fibrosis, bronchiectasis, bullae, emphysema, nodular or lymphomatous abnormalities. "The renin–angiotensin axis plays an important and multi-dimensional role in pulmonary vascular changes in both acute and chronic lung disease." (PMID 33537342, 2020).
clear cell renal carcinoma (3 papers, 2021 to 2025). A malignant epithelial neoplasm of the kidney characterized by the presence of lipid-containing clear cells within a vascular network. "This study investigated the expression of components of the renin-angiotensin system (RAS) by cancer stem cells (CSCs) we have recently demonstrated in renal clear cell carcinoma (RCCC)." (PMID 33916968, 2021).
delirium (3 papers, 2020 to 2025). A disorder characterized by confusion; inattentiveness; disorientation; illusions; hallucinations; agitation; and in some instances autonomic nervous system overactivity. "Matched cohorts: Incidence of delirium over a two-year period associated with calcium channel blockers (CCBs) compared to diuretics, renin-angiotensin system (RAS) agents and beta-blockers." (PMID 32638634, 2020). "Refined cohorts: Incidence of delirium over a two-year period associated with calcium channel blockers (CCBs) compared to diuretics, renin-angiotensin system (RAS) agents and beta-blockers." (PMID 32638634, 2020). "Calcium channel blockers are associated with higher rates of delirium than renin-angiotensin system agents, but lower rates compared to beta-blockers." (PMID 32638634, 2020). "While calcium channel blockers have been reported to be associated with a higher rate of delirium than renin–angiotensin system agents (∼40% higher) but less common than in beta blockers (20% lower), no specific information about dosing, and so forth is provided beyond the generic statement [S38]." (PMID 40686036, 2025). "Delirium was more common with calcium channel blockers than with renin-angiotensin system agents (~40% higher) but less common than with beta-blockers (~20% lower)." (PMID 32638634, 2020).
diabetic autonomic neuropathy (3 papers, 2018 to 2025). Autonomic neuropathy that is caused by diabetes mellitus. "Additionally, diabetic autonomic neuropathy contributes to a reduction in catecholamine-induced stimulation of renin release." (PMID 40106408, 2025). "The resulting pathophysiological changes include impaired myocardial relaxation and cardiomyocyte resting tension, activation of the renin–angiotensin system (leading to vasoconstriction, salt and water retention, and fibrosis) and diabetic autonomic neuropathy." (PMID 29368650, 2018).
diabetic neuropathy (3 papers, 2021 to 2026). A chronic, pathological complication associated with diabetes mellitus, where nerve damages are incurred due to diabetic microvascular injury involving small blood vessels that supply these nerves, resulting in peripheral and/or autonomic nerve dysfunction. "The direct renin inhibitor aliskiren is recognized as a treatment for cardiovascular disease in diabetic patients, but little is known about its potential benefits in cases of diabetic neuropathy." (PMID 33855212, 2021).
diastolic heart failure (3 papers, 2013 to 2021). Heart failure caused by abnormal myocardial relaxation during diastole leading to defective cardiac filling. "The activation of the renin‐angiotensin‐aldosterone system promotes LV remodeling regardless of its etiology and eventually leads to systolic or diastolic heart failure." (PMID 33998163, 2021).
gastric cancer (3 papers, 2017 to 2025). A primary or metastatic malignant neoplasm involving the stomach. "The mechanistic association between proteinuria and gastric cancer development can be explained by dysregulation of the renin-angiotensin system (RAS)." (PMID 40940839, 2025).
Gordon syndrome (3 papers, 2018 to 2024). An extremely rare multiple congenital malformation syndrome characterized by congenital contractures of hand and feet with variable degrees of severity of camptodactyly, clubfoot and, less frequently, cleft palate. "The classical genetic syndromes that result in a low renin and aldosterone phenotype are rare, and include classical AME, activating mutations in the MR or ENaC (Liddle syndrome), atypical forms of CAH, Gordon syndrome, and glucocorticoid resistance syndrome." (PMID 29439489, 2018).
graft versus host disease (3 papers, 2021 to 2025). An immune system disorder that occurs after allogeneic hematopoietic stem cell transplant and is a reaction of donor immune cells against host tissues. "The present study was designed to investigate the role of myofibroblast transdifferentiation and the conjunctival renin–angiotensin system (RAS) in the pathogenesis of graft-versus-host disease (GVHD)–associated conjunctival fibrosis." (PMID 34643664, 2021).
hemangioma (3 papers, 2020 to 2024). A benign vascular lesion characterized by the formation of capillary-sized or cavernous vascular channels. "Although its exact mechanism of action on hemangiomas is unclear, it has been hypothesized to involve vasoconstriction, the inhibition of angiogenesis, the induction of apoptosis, the inhibition of nitric oxide production, and the regulation of the renin–angiotensin system." (PMID 38893043, 2024). "In vascular endothelial cells, propranolol is considered to induce vascular contraction by suppressing NO production, inhibit renin production, control angiogenesis by regulating the expression of VEGF•bFGF•MMP2/MMP9, and induce apoptosis, but it may also affect pericytes and hemangioma stem cells." (PMID 32202048, 2020).
hepatitis C (3 papers, 2019 to 2025). "Recipient risk factors associated with graft failure include age, increasing plasma renin activity, BMI, prior transplant, dialysis at the time of KT, and hepatitis C virus infection." (PMID 31847814, 2019).
hyperandrogenism (3 papers, 2017 to 2026). Excessive secretion of androgens from the adrenal glands or gonads. "It is associated with hyperandrogenism in women and can be also associated with increased activity of the renin-angiotensin system (RAS)." (PMID 28042549, 2017).
hyperplasia (3 papers, 2012 to 2024). An abnormal increase in the number of cells in an organ or a tissue with consequent enlargement. "In two patients, the aldosterone (ng/dL)/renin (ng/mL/h) relationship was over 30, and only one showed an abnormality in adrenal tomography (hyperplasia)." (PMID 23320147, 2012).
hypertensive retinopathy (3 papers, 2023 to 2025). Retinopathy due to hypertension. "Both the sympathetic nervous system and the renin–angiotensin system play a pivotal role in the pathogenesis of hypertensive retinopathy." (PMID 36986445, 2023). "Hypertensive retinopathy pathologies arise normally due to oxidative stress, ischemia, endothelium dysfunction, inflammation, and an activated renin–angiotensin system (RAS) and catecholamine which are vasoconstrictors in their biological nature." (PMID 36986445, 2023).
leukemia (3 papers, 2018 to 2020). A malignant (clonal) hematologic disorder, involving hematopoietic stem cells and characterized by the presence of primitive or atypical myeloid or lymphoid cells in the bone marrow and the blood. "To assess the influence of mouse strain on leukemia development, we generated control and mutant mice using two different renin-Cre animals: one generated in pure SV background mice, ‘Ren1dCre(SV)’, and another backcrossed for over 15 generations in Bl6 background mice, ‘Ren1dCre(Bl6)’." (PMID 30467111, 2018). "Thus, the incidence and timing of leukemia development in this model are sensitive to the efficiency of RBP-J deletion within renin-expressing cells." (PMID 30467111, 2018). "Thus, it may be that Bl6 animals have more renin-expressing hematopoietic cells undergoing deletion of RBP-J at an earlier age, and leukemia development in this model occurs in a time-dependent manner." (PMID 30467111, 2018).
Marfan syndrome (3 papers, 2015 to 2025). A disorder of the connective tissue. "Patients with vEDS are often empirically treated with beta-blocker or renin–angiotensin–aldosterone blockers that were proven to be beneficial in Marfan syndrome." (PMID 40559232, 2025). "In Marfan’s syndrome, which is characterized by a fibrillin-1 gene mutation and excessive TGF-β leading to the development of aortic arch aneurysm and dissection, it is not clear if targeting the renin–angiotensin system can be beneficial." (PMID 32664652, 2020).
medulloblastoma (3 papers, 2014 to 2022). A malignant, invasive embryonal neoplasm arising from the cerebellum. "KCTD11 (REN) is a tumor suppressor gene mapping on human chromosome 17p13.2, whose expression is frequently lost in human medulloblastoma and in several other cancer types." (PMID 25045667, 2014). "As a result of the disruption of REN tumor suppression function shown in human medulloblastoma, the issue of whether this gene is involved in the formation of cerebellar GCPs has been raised." (PMID 35481240, 2022).
memory impairment (3 papers, 2017 to 2023). "Notably, CYP27A1-overexpressing mice that produce increased levels of 27-OH develop memory impairment due to, e.g., reduction in neuronal glucose uptake, impaired neuronal branching and reduced synaptic density, inflammation and impairment of the brain renin-angiotensinogen system." (PMID 33676572, 2021). "Along with memory impairment, CYP27A1 tg mice have an upregulated brain renin-angiotensin system and reduction in dendritic arborization, spine density of the hippocampus, and levels of long-term memory-related protein Arc (activity-regulated cytoskeleton-associated protein)." (PMID 33676572, 2021).
mental disorder (3 papers, 2020 to 2022). A disease that has its basis in the disruption of mental process. "An interesting and currently poorly understood area is the influence of RAS on the functioning of the brain in the context of behavior, response to external stimuli, or the influence of the renin-angiotensin system on the occurrence of psychiatric diseases." (PMID 33673178, 2021). "Regarding mental disorders and AF, imbalances in the autonomic nervous system, inflammatory processes, and renin-angiotensin-aldosterone system may play roles in the induction of new-onset AF." (PMID 36397079, 2022).
neuroblastoma (3 papers, 2011 to 2022). Neuroblastoma (NB) is the most common solid, extracranial childhood tumor. "We recently reported that IH increases renin expression in juxtaglomerular cells, as well as the expression of dopamine β-hydroxylase and phenylethanolamine N-methyltransferase in catecholamine-synthesizing neuroblastoma cells, causing SAS patients to become hypertensive." (PMID 35955916, 2022).
peripheral vascular disease (3 papers, 2022 to 2025). Any disorder affecting blood flow through the veins or arteries outside of the heart. "Toxin accumulation, renin-angiotensin system activation, increased oxidative stress, and proinflammatory cytokines increase the susceptibility of CKD patients to peripheral vascular disease and wound infection." (PMID 40121456, 2025). "2.Vascular damage: fluid retention, renin-angiotensin system changes, oxidative stress resulting in more serious peripheral vascular disease aggravated ischemic ulcers." (PMID 40162314, 2025). "For example, having a preceding pathology in which renin–angiotensin system (RAS) and vascular endothelium damage (i.e. chronic renal, lung, cardiovascular, cerebrovascular or peripheral vascular diseases) plays a significant role in both." (PMID 35709192, 2022).
Peritoneal Fibrosis (3 papers, 2012 to 2023). Disorder characterized by a wide range of structural changes in PERITONEUM, resulting from fibrogenic or inflammatory processes. "In accordance with this, in animal models, administration of renin inhibitor aliskiren decreased the severity of CG-induced peritoneal fibrosis." (PMID 37762068, 2023). "In this report, we provide evidence for the in vitro and in vivo participation of the renin-angiotensin-aldosterone system (RAAS) in the signaling pathway leading to peritoneal fibrosis during PD." (PMID 22558414, 2012). "Furthermore, recent experimental and human data suggest the role of the activation of the peritoneal renin–angiotensin–aldosterone system (RAAS) in peritoneal fibrosis." (PMID 37762068, 2023).
Pleural effusion (3 papers, 2011 to 2020). The presence of an excessive amount of fluid in the pleural cavity. "ANP infusion decreased renin and aldosterone and pleural effusion compared with controls." (PMID 22032777, 2011).
Proteinuria (3 papers, 2013 to 2024). Increased levels of protein in the urine. "Proteinuria is sensitive to glomerular hypertension and is a marker of renal function; thus, reduced glomerular pressure during nonextreme high ambient temperature may alleviate proteinuria by blocking the renin-angiotensin-aldosterone system." (PMID 38899224, 2024).
renal tubular disorder (3 papers, 2017 to 2025). "Regarding renal tubular disorders, CKD has increasingly been recognized in these patients, potentially driven by persistent volume depletion and activation of the renin-angiotensin-aldosterone system." (PMID 40924182, 2025).
renal tubular dysgenesis (3 papers, 2021 to 2024). "Genetic loss of function of AGT (angiotensinogen), REN (renin), ACE (angiotensin-converting enzyme), or AGTR1 (type-1 angiotensin II receptor) leads to renal tubular dysgenesis (RTD)." (PMID 33768328, 2021).
retinal ischemia (3 papers, 2022 to 2024). A ischemic disease that involves the retina. "However, prevention of retinal ischemia-reperfusion injury can be achieved by administering a direct renin inhibitor, ACE inhibitor, AT1-R antagonist, or MR antagonist." (PMID 35453295, 2022). "Moreover, ACE2 is a major converting enzyme in the vascular protective axis of the renin-angiotensin system in the retina, and its downregulation may lead to retinal ischemia, which is related to microangiopathy, retinitis, and retinal degeneration." (PMID 38909148, 2024).